MT-TA (mitochondrially encoded tRNA-Ala (GCN))
Synonyms: trnA; formerly MTTA
Gene: Mitochondrial transfer RNA gene on chromosome MT (5,587 to 5,655, reverse strand). Ensembl gene ENSG00000210127.
Gene-disease validity (ClinGen):
ClinGen rates the evidence that MT-TA causes each of these diseases.
mitochondrial disease (mitochondrial): Definitive.
Homologues: Orthologues: chimpanzee MT-TA (100% identical).
Diseases named in the same sentence as MT-TA in open-access papers:
MT-TA is named in the same sentence as 5 diseases in open-access papers, as found by Europe PMC text mining. Sharing a sentence is not in itself a finding about the gene and the disease.
MT-TA shares sentences with these, for which no sentence is quoted: Colon Cancer (1 paper); genetic diseases (1); scleroderma (1); tumor (1); viral infection (1).